IL22 (interleukin 22)
Diseases named in the same sentence as IL22 in open-access papers (continued):
Sharing a sentence is not in itself a finding about the gene and the disease.
pneumococcal infection (6 papers, 2021 to 2025). Infections with bacteria of the species streptococcus pneumoniae. "A recent study revealed that human tissue showed enhanced titers of IL-17 and IL-22 in response to pneumococcal infection." (PMID 38711516, 2024). "The authors suggested that IL-22:Fc, a recombinant fusion protein containing human IL-22 and immunoglobulin G2 (IgG2)-Fc might be a novel adjunct therapy for severe pneumococcal infection." (PMID 33718260, 2021). "In addition, mice with pneumococcal infection treated with IL-22:Fc had decreased infection burden in both the lung and liver, with increased C3 binding." (PMID 34597299, 2021). "In Streptococcus pneumoniae infections, ILC3 accumulate in the lungs, providing IL-22 and aiding in infection resolution." (PMID 40568578, 2025). "In the lung, IL22 producing ILC3 protect against allergic airway disease and Streptococcus pneumoniae infection." (PMID 34906172, 2021). "The absence of IL-22 makes the host vulnerable to pneumococcal infection, which indicates that the presence of IL22 is very important to control pneumococcal infection." (PMID 35967401, 2022).
Pruritus (6 papers, 2018 to 2025). Pruritus is an itch or a sensation that makes a person want to scratch. "Skin RNA sequencing of patients with severe pruritus in PN revealed robust upregulation of Th22-related genes and signaling pathways, including IL-22, IL-22 receptors (IL22RA1 and IL22RA2), and IL-22-associated cytokines." (PMID 38077377, 2023). "The lack of difference in pruritus intensity between AD subgroups may be due to their secretion of comparable levels of IL-4, IL-22 and IL-31, as well as similar levels of tryptase." (PMID 40869144, 2025).
respiratory infections (6 papers, 2016 to 2025). "So far, IL-33 signaling was more studied in the respiratory system and found to modulate IL-22-dependent antibacterial defense during respiratory infection." (PMID 38533053, 2024). "These genes are directly involved in innate immune sensing (TLR, MYD88, JAK/STAT), and inflammation (IL-6, IFN, TNF, IL-10, IL-22) which are two common host signaling pathways activated by bacteria and viruses during acute respiratory infections." (PMID 27532264, 2016). "Some investigations indicate a protective role of IL-22 in respiratory infections, however, its link with TB is still not completely understood." (PMID 35407608, 2022).
schizophrenia (6 papers, 2013 to 2025). A major psychotic disorder characterized by abnormalities in the perception or expression of reality. "IL-22 has both protective and harmful effects, which is why it needs to be studied more about schizophrenia." (PMID 41200225, 2025). "We recently created a novel neuroimmunotoxic pathway index in schizophrenia, particularly deficit schizophrenia, by connecting IL-6, IL-23, and IL-17 to critical actors such as IL-21, IL-22, and TNF-α." (PMID 36429996, 2022). "Compared to controls, schizophrenia patients had much higher levels of IL-22 in this study." (PMID 41200225, 2025). "Recombinant human IL-22 could ameliorate the outcome of schizophrenia by limiting bacterial translocation and by initiating tissue repair." (PMID 39596179, 2024). "Based on the hypothesis presented here, we discuss alternative schizophrenia interventions, including AhR antagonists, mitochondrial transplant, membrane lipid replacement, and recombinant human IL-22." (PMID 39596179, 2024). "Nevertheless, there is no data on whether the IL-6, IL-23, and Th17 (IL-17, TNF-α, IL-21 and IL-22) axis is more associated with MNP than with SNP and whether changes in this axis are associated with the G-CoDe and the phenome of schizophrenia." (PMID 36256663, 2022). "IL-1β, IL-22, G-CSF, IL-21, and IL-10 were significantly higher in schizophrenia than in controls." (PMID 36256663, 2022). "By inference, the strong effects of the IL-6/IL-23/Th17 axis on both the cognitive detrioration and symptomatome of schizophrenia indicate that IL-23, Th17, IL-22 and IL-21 may further contribute to the neurotoxic effects." (PMID 36256663, 2022). "Ratios of cytokine concentrations within the same axis may also be a marker of immune pathway activation, as has been reported for IL-17/TGF-β ratio in schizophrenia or IL-17F/IL-22 ratio in chronic hepatitis C virus infection." (PMID 23968496, 2013). "The first major finding of this study is that IL-23, IL-6, IL-17, and TNF-α were considerably greater in MNP than in SNP, while IL-1β, IL-22, G-CSF, IL-21, IL-17, IL-10, and TNF-α were significantly higher in schizophrenia than in controls." (PMID 36256663, 2022). "This study aimed to examine serum levels of Th17-related cytokines (IL-17, IL-21, IL-22, IL-23) and chemokines (CCL2, CCL5, CCL20, CXCL10, IL-8) in schizophrenia patients compared to healthy controls and to explore their associations with symptom severity and laboratory parameters." (PMID 41200225, 2025). "The present study compares the serum levels of selected cytokines and chemokines—IL-17, IL-22, IL-23, IL-8, IL-21, CCL20, CXCL10, CCL2and CCL5—in schizophrenia patients to healthy controls due to growing evidence linking immune-inflammatory and metabolic dysregulation to schizophrenia." (PMID 41200225, 2025). "Increased IL-22 and IL-6, but not IL-17 or IL-1β, were observed in schizophrenia as compared with healthy subjects." (PMID 36256663, 2022). "Furthermore, increased levels of IL-1β, IL-6, IL-17, IL-21, IL-22, IL-23, and tumor necrosis factor (TNF)-α were all found to be inversely related to HR-QoL in these schizophrenia patients." (PMID 36011997, 2022). "Most importantly, during inflammatory responses, IL-22 is upregulated in the brain and may increase the production of TNF-α, IL-6, and prostaglandins and induce STAT3, MAP-kinase, and JAK-STAT pathways, which all play a role in schizophrenia." (PMID 36256663, 2022).
thymic atrophy (6 papers, 2015 to 2024). "In an early study, injection of mice with adenovirus expressing IL-22, which produced super high levels of circulating IL-22, induced marked body weight loss and thymic atrophy in lean mice." (PMID 26064446, 2015). "As for chronic age-induced thymic atrophy, IL-22 may offer more benefits for improved thymic microenvironment since one study saw correlative up-regulation of IL-22 and FOXN1 after acute thymic insult in mice." (PMID 31988649, 2020). "LPS stimulation also has been shown to induce the expression of another inflammatory factor IL22 in vivo, and overexpression of IL22 alone could induce thymic atrophy in mice." (PMID 27142675, 2016). "However, the improvement of MASLD symptoms with safe doses of IL-22 is limited, while higher concentrations of IL-22 may produce off-target toxicity or induce cachexia, such as thymic atrophy and proximal tubule lesions." (PMID 39166109, 2024). "Furthermore, IL-22 is reported to drive endogenous thymic regeneration 43, and TP5 alleviated DSS-induced thymic atrophy, thus thymus could supply more T cells to peripheral tissues to maintain immune homeostasis after TP5 treatment, forming a positive feedback loop." (PMID 31695782, 2019).
thymoma (6 papers, 2010 to 2025). A neoplasm arising from the epithelial cells of the thymus. "Kisand and colleagues reported on a cohort of 162 patients with APECED and described anti-IL-17A, IL-17F and/or IL-22 AAbs in over 90% of cases, and additionally detected high titer IL-17A and IL-22 AAbs in two patients with thymoma and CMC." (PMID 31557985, 2016). "Consensually, anti-cytokine antibodies against type I IFNs, IL-12, IL-17, and IL-22 are found in APS-1 or myasthenia gravis patients associated with or without thymoma." (PMID 21079687, 2010). "Interestingly, anti-IL-17 and anti-IL-22 antibodies were also found in CMC patients with thymomas with aberrant expression of AIRE, suggesting that dysregulation of central tolerance drives the generation of anti-cytokine antibodies and subsequent CMC development." (PMID 31548517, 2017). "Three of the anti‐IL‐6 positive thymoma patients also had autoantibodies against IFN‐α2a, IL‐17s, and/ or IL‐22." (PMID 27957331, 2016). "At least in APECED and thymoma, the development of cytokine autoantibodies is not limited to IFNs as they develop autoantibodies to other cytokines including IL-17A, IL-17F, IL-22, IL-12, and IL-1A." (PMID 40304722, 2025). "In addition to IL-17 and IL-22 antibodies, APECED patients demonstrated autoantibodies specific for IL-6, whereas IL-23 autoantibodies were present in approximately 27.9% of thymoma patients but not in APECED patients." (PMID 31548517, 2017).
ZIKV infection (6 papers, 2018 to 2025). "In this study with ZIKV infection, we found that IL-22 deficiency resulted in decreased viral loads, alleviated clinical manifestations, and increased survival rates in neonatal mice." (PMID 32843067, 2020). "We found that γδ T cells were the main source of IL-22 during ZIKV infection in both the spleen and brain." (PMID 32843067, 2020). "To determine the role of IL-22 in the microglial profile during ZIKV infection, we analyzed the microglial phenotype in both WT and IL-22-/- neonatal mice." (PMID 32843067, 2020). "To elucidate the role of IL-22 in ZIKV infection, we s.c. infected 1-day-old WT B6 and IL-22-/- mice and monitored their bodyweight changes, survival rates, and clinical signs." (PMID 32843067, 2020). "Although ZIKV infection significantly inhibited cell growth and elevated inflammatory gene expression, supplementing with IL-22 was dispensable for cell proliferation and activation." (PMID 32843067, 2020). "In addition to these cytokines, GM-CSF, IL-1B, IL-2, IL-6, IL-17, and IL-22 have been observed in the acute phase of Zika virus infection." (PMID 41417343, 2025). "Therefore, our data demonstrated that ZIKV infection induced activation of astrocytes and microglia, leading to brain inflammation, while IL-22 was dispensable for glial cell activation and viral clearance in vitro." (PMID 32843067, 2020). "In line with recent findings that CD8+ T cells protected against ZIKV infection in the CNS, our finding suggests that IL-22 may contribute to ZIKV encephalitis pathogenesis via modulating periphery CD8+ T cell responses." (PMID 32843067, 2020). "To investigate whether ZIKV infection can induce IL-22 expression, we infected 3-week-old IFNAR-/- mice with ZIKV as previously reported." (PMID 32843067, 2020). "Indeed, ZIKV infection induced high levels of brain inflammatory cytokines, including IL-1β, which may facilitate the expression of IL-22 from γδ T cells." (PMID 32843067, 2020). "Thus, our results indicated that ZIKV infection can induce IL-22 expression by γδ T cells." (PMID 32843067, 2020). "The cellular source of IL-22 was identified in IFNAR-/- mice and wild-type (WT) neonatal mice during ZIKV infection." (PMID 32843067, 2020). "Future studies of selective inhibition or supplementation of IL-22 and PDGF-BB in our culture system will help to address their actual contribution to inhibition of ZIKV infection of the vaginal mucosa." (PMID 30692980, 2018). "Furthermore, inflammation resulting from ZIKV infections can lead to increased pathology, such as fetal growth malformations observed in ZIKV-infected pregnant mothers with high levels levels of IL22, MCP-1, TNFa, IP10." (PMID 34120576, 2021). "Although we observed neutrophil infiltration in the brain during ZIKV infection, the absence of IL-22 did not change the number of infiltrated neutrophils (data not shown)." (PMID 32843067, 2020). "Additional evidence is that IL-22 deficiency did not influence WNV burdens in the spleen; however, IL-22-/- mice had lower viral loads in the spleen following ZIKV infection." (PMID 32843067, 2020). "Taken together, our studies demonstrated that ZIKV infection promoted microglia and astrocyte activation, whereas the absence of IL-22 resulted in reduced glial cell activation and improved clinical signs of disease in a neonatal mouse model of ZIKV encephalitis." (PMID 32843067, 2020). "Further analysis revealed that ZIKV infection resulted in microglial hyper-ramification; however, the process length of microglia in IL-22-/- mice was shorter than those in WT mice, indicating reduced microglia activation in the absence of IL-22." (PMID 32843067, 2020). "No considerable IL-22 upregulation was observed in the lung and liver following ZIKV infection." (PMID 32843067, 2020).
ZIKV infection (continued). "Infection of both WNV and ZIKV in IL-22-/- mice led to alleviated clinical manifestations with decreased viral load and elevated pro-inflammatory TNF-α expression in the brain, whereas rIL-22 cytokine treatment in vivo played a detrimental role in ZIKV infection." (PMID 32843067, 2020).
acute lung injury (5 papers, 2017 to 2025). A condition of lung damage that is characterized by bilateral pulmonary infiltrates (pulmonary edema) rich in neutrophils, and in the absence of clinical heart failure. "We evaluated the levels of key cytokines, including TNF-α, IL-6, IL-1β, IL-10, IL-17, IL-22, IFN-γ, and TGF-β1, which play central roles in the inflammatory cascade associated with LPS-induced acute lung injury (ALI)." (PMID 41280422, 2025). "These pre-clinical data suggest that IL-22 may have therapeutic potential in other forms of acute lung injury (ALI)." (PMID 34597299, 2021). "Since IL-22 has been shown to have therapeutic potential by decreasing lung inflammation and injury in a murine model of H1N1 influenza, we hypothesized that the IL-22 protein given after acute lung injury (ALI) in mice would mitigate inflammation and repair ARDS-associated lung injury." (PMID 34597299, 2021).
allergic contact dermatitis (5 papers, 2011 to 2024). An inflammatory skin condition caused by an immune response to direct contact between the skin and an allergen. "In line with this, dysregulation of IL-22 and/or IL-22-producing cells is associated with AD and allergic contact dermatitis." (PMID 38396697, 2024). "To assess their role in ACD, we set up a mouse model of PPD-induced allergic contact dermatitis and we showed that, in contrast to Il22-deficient mice, Il22ra1-, Il20rb- and Il24-deficient mice are partially protected against development of PPD-induced contact hypersensitivity." (PMID 30755657, 2019).
anaplastic large cell lymphoma (5 papers, 2013 to 2021). Anaplastic large cell lymphoma (ALCL) is a rare and aggressive peripheral T-cell non-Hodgkin lymphoma, belonging to the group of CD30-positive lymphoproliferative disorders, which affects lymph nodes and extranodal sites. "Also, the aberrant expression of IL-22R1 and autocrine IL-22 stimulation contribute to tumorigenicity in anaplastic large cell lymphoma." (PMID 23519428, 2013).
chronic GVHD (5 papers, 2016 to 2024). "Associated with T lymphocytes, IFNγ and TNFα are core cytokines of chronic GvHD pathogenesis, and IL-6 and IL-22 aggravate skin lesions." (PMID 39131155, 2024). "In humans, it was reported that the expression of IL-22 in peripheral blood mononuclear cells was elevated in pediatric patients who had active chronic GVHD." (PMID 28945764, 2017). "In a chronic GVHD murine model, Okamoto’s group reported that more than 70% of IL-22-producing cells are CD4+ T cells." (PMID 27148267, 2016). "In active chronic GVHD pediatric patients, a recent report demonstrated an increase of IL-22 expression in peripheral blood mononuclear cells as compared to that in patients with no GVHD." (PMID 27148267, 2016). "The PSGL1hi Th1, Th2, and Th17 cross-reactive autoreactive Trm cells interact with DCs and macrophages to mediate chronic GVHD pathogenesis via their production of cytokines such as TGF-β, IFN-γ, TNF-α, IL-4, IL-17, and IL-22." (PMID 34539630, 2021). "Recently, a report showed that SOCS1 expression was abolished in acute or chronic GVHD patients, suggesting that IL-22-induced STAT1 is no longer inhibited in this context." (PMID 27148267, 2016).
chronic hepatitis C (5 papers, 2012 to 2024). "This study investigates the immunopathogenic impact of the cytokines IL-17 and IL-22 in OHCV infection compared to chronic hepatitis C (CHC) infection." (PMID 38273234, 2024). "In another study, chronic hepatitis C patients presented elevated serum levels of IL-10, IFN-γ, IL-6, and IL-4, while IL-1, IL-2, IL17, IL-22, IL-13 TNF, IL-12p70, and IL-15 levels were lower in patients compared to healthy controls." (PMID 29977152, 2018).
chronic kidney disease (5 papers, 2017 to 2024). Impairment of the renal function secondary to chronic kidney damage persisting for three or more months. "Data from other human cohorts are not available, so that further studies are necessary to confirm the inverse association between IL-22 and eGFR and to explore the relevance of this association for the development of chronic kidney disease in older individuals." (PMID 28143481, 2017). "Overall, IL-22 promotes renal regeneration through epithelial cell proliferation as one of several promising strategies for treating (or avoiding) end-stage renal diseases." (PMID 35432360, 2022). "The findings of this study, however, show that IL‐22‐dependent AKT activation is beneficial in chronic kidney disease via increasing tubular cell survival while other cell types are not affected." (PMID 30156011, 2018). "To explore the changes of IL‐22 expression in the course of chronic kidney disease, we performed renal IL‐22 immunohistochemical staining 1 day, 5 days and 10 days upon UUO in BALB/c mice." (PMID 30156011, 2018). "It is tempting to speculate that the effects seen in obstructive nephropathy can be extrapolated to other forms of chronic kidney diseases, making IL‐22 a potential therapeutical option to specifically target tubular epithelial cells." (PMID 30156011, 2018). "Nevertheless, it is unknown whether IL‐22 also plays a role in subacute or chronic kidney disease, where typically there is less inflammation." (PMID 30156011, 2018). "IL‐22, a member of the IL‐10 cytokine family, accelerates tubule regeneration upon acute kidney injury, hence we speculated on a protective role also in chronic kidney disease." (PMID 30156011, 2018).
food allergy (5 papers, 2012 to 2025). Gastrointestinal disturbances, skin eruptions, or shock due to allergic reactions to allergens in food. "However, the important point is that significant associations between IL-22 mRNA expression and PCBs are found only among children showing positive IgE reactions to milk and egg (i.e., a food allergy)." (PMID 23330224, 2012). "In a food allergy mouse model, disruption of the tryptophan pathway suppressed Reg3g and IL-22 expression and disturbed intestinal immune homeostasis." (PMID 41395465, 2025). "Based on this retrospective approach, we identified 3 distinct features of animals protected from food allergy development: 1) a tight intestinal epithelium, 2) elevated levels of IL-22 and 3) a distinct microbial composition." (PMID 27789346, 2016). "In addition, experimental research has shown that several members of the Lachnospiraceae protect against food allergy through stimulating the production of IL-22 which reinforces the epithelial barrier to reduce gut permeability to dietary proteins." (PMID 39203888, 2024).